MMP1 (matrix metallopeptidase 1)
Diseases named in the same sentence as MMP1 in open-access papers (continued):
Sharing a sentence is not in itself a finding about the gene and the disease.
collagen diseases (1 paper, 2013). "Theratio of MMP-3 to MMP-1 was also reduced in the AoDILD state in these patients.These biomarker profiles were similar to that of collagen disease patients withAoDILD." (PMID 23405989, 2013). "Thus, the MMP-3 to MMP-1 ratio, and levels of TIMP-3, MMP-9, andosteopontin could be prognostic markers for AoDILD in collagen diseases." (PMID 23405989, 2013).
colorectal adenoma (1 paper, 2006). An adenoma that arises from the colon or rectum. "To explore whether MMP1, MMP3 and MMP7 gene promoter polymorphisms are involved in the early step of colorectal carcinogenesis, we investigated the relation between these polymorphisms and the risk of colorectal adenoma in a case-control study." (PMID 17125518, 2006).
complication (1 paper, 2015). Any disease or disorder that occurs during the course of, or because of, another disease, treatment, or procedure. "Levels of HbA1c, LDL, triglycerides, MMP-1, MMP-2, MMP-3, MMP-9, MMP-10, TIMP-1 and markers of LGI and ED were significantly higher in individuals with vascular complications compared to those without." (PMID 25848912, 2015).
coronary stenosis (1 paper, 2013). Narrowing of the coronary artery lumen diameter. "Other univariate analyses show that significant coronary stenosis (above 75%) was related to seven polymorphisms: C667T MTHFR, K469E ICAM1, –1607 1G/2G MMP1, –1612 5A/6A MMP3, K167N LOX-1, –675 4G/5G PAI, and IVS7 FVII." (PMID 23274712, 2013).
diverticulitis (1 paper, 2024). An infection that develops in the diverticula of the intestinal tract. "Whilst a collagen deficit does not identify individuals who will go on to develop diverticulitis, one study demonstrated downregulation of MMP2, MMP9 and MMP13 expression and an increase in MMP1, TIMP1 and TIMP3 in inflamed mucosa of patients with diverticulitis versus Crohn’s disease." (PMID 38831715, 2024).
Follicular Cyst (1 paper, 2022). Cyst due to the occlusion of the duct of a follicle or small gland. "Moreover, the decreased expression of ovarian matrix metallo proteinase 1/2 (MMP1/2) is an important marker of the occurrence of follicular cysts in cows." (PMID 36311668, 2022).
gastrointestinal stromal tumours (1 paper, 2024). "Similarly, enhanced secretion of exosomal MMP-1 promotes tumour cell invasion in gastrointestinal stromal tumours (GIST)." (PMID 38200509, 2024).
giant cell arteritis (1 paper, 2024). "Additionally, we found that elevated levels of Tie-2 are associated with an increased risk of giant cell arteritis, while elevated levels of MMP-1 are associated with a decreased risk of giant cell arteritis." (PMID 39253091, 2024). "However, studies on the role of MMP-1 in giant cell arteritis triggered by VZV reactivation are limited, and our research findings provide a different avenue for investigation." (PMID 39253091, 2024).
hemorrhage (1 paper, 2020). Loss of blood from the vascular compartment to the exterior or into nonvascular body space as a result of rupture or severance of the blood vessels. "CD163 mRNA expression displayed a weak increasing trend to macrophages, and moderate increasing trends to lipids and intraplaque hemorrhage, as well as to MMP-1 and MMP-9." (PMID 32873809, 2020).
hepatitis C infection (1 paper, 2020). "The top five degrees of the potential targets for the YCHD in the treatment of hepatitis C include PIK3CG, CASP3, BCL2, CASP8, and MMP1." (PMID 32050950, 2020).
hereditary gingival fibromatosis (1 paper, 2024). Hereditary gingival fibromatosis (HGF) is a rare benign, slowly progressive, non-inflammatory fibrous hyperplasia of the maxillary and mandibular gingivae that generally occurs with the eruption of the permanent (or more rarely the primary) dentition or even at birth. "Decreased MMP1, but not TIMP1, production was indeed previously associated with hereditary gingival fibromatosis (HGF), a genetically heterogeneous condition characterized by pathological fibrosis of gingival tissue and abundant production of type I collagen and VIM91." (PMID 38664418, 2024).
hydronephrosis (1 paper, 2020). Collection of urine in the renal pelvis that results in dilatation of the renal pelvis and calyces. "This study evaluates serum and urinary metalloproteinases MMP-1, MMP-2, and MMP-9 and tissue inhibitors of metalloproteinases TIMP-1 and TIMP-2 as potential biomarkers of ON in children with congenital unilateral hydronephrosis (HN) caused by UPJO." (PMID 32670438, 2020).
Hypercholesterolemia (1 paper, 2022). An increased concentration of cholesterol in the blood. "Hypercholesterolemia may alter MMP1 and ADAMTS5 expression in the synovium of the glenohumeral joint." (PMID 35168639, 2022). "Hypercholesterolemia may alter MMP1 and ADAMTS5 expression in synovium of the glenohumeral joint." (PMID 35168639, 2022). "Therefore, hypercholesterolemia altered synovial MMP1 and ADAMTS5 levels in the glenohumeral joint." (PMID 35168639, 2022).
Hyperinsulinemia (1 paper, 2023). An increased concentration of insulin in the blood. "HbA1c correlated positively with changes of MCP-2 and IL-15-RA during hyperinsulinemia (Rho ≥ 0.51) and inversely with changes of CXCL1, MMP-1 and Axin-1 during hypoglycemia (Rho ≤ -0.55)." (PMID 37400734, 2023).
hyperlipidemia (1 paper, 2021). "Similarly, ESR1(ERα), MAOA, MGAM, PTK2, MMP1, GNB5, PIK3R3, and other targets had higher degree values, suggesting that these genes might be the core targets of PCE intervention in hyperlipidemia." (PMID 34925692, 2021).
hypospadias (1 paper, 2024). Hypospadias is the displacement of the urethral meatus on the ventrum of the penis. "Decreased MMP-1 levels in hypospadias are linked to increased collagen production." (PMID 39476852, 2024). "The proteins fibulin-1, elastin, matrix metalloproteinase-1 (MMP-1), basic fibroblast growth factor (bFGF or FGF-2), and α-smooth muscle actin (α-SMA) play roles in hypospadias development." (PMID 39476852, 2024). "Therefore, this protocol is designed to investigate the differences in mRNA expression of fibulin-1, elastin, MMP-1, bFGF, and α-SMA between the ventral and dorsal tunica dartos in patients with hypospadias and chordee." (PMID 39476852, 2024).
intestinal tumour (1 paper, 2003). "A number of different MMPs may be important in intestinal tumour formation as human tumours have been shown to express interstitial collagenase (MMP-1), gelatinase A (MMP-2), stromelysin 1 (MMP-3), matrilysin (MMP-7), gelatinase B (MMP-9), and stromelysin 3 (MMP-11)." (PMID 12778076, 2003).
intracerebral hemorrhage (1 paper, 2023). A cerebrovascular disorder characterized by bleeding into one or both cerebral hemispheres including the basal ganglia and the cerebral cortex. "Moreover, males exhibit increased levels of matrix metalloproteinases (MMP-1,2,3 and 9) in blood serum after intracerebral hemorrhage whereas changes in females were minimal." (PMID 37428916, 2023).
intraventricular haemorrhage (1 paper, 2026). "The objective of the present study is to examine the association between the presence of various forms of matrix metalloproteinase genes (MMP-1, MMP-9, TIMP-1 and TIMP-2) and their tissue inhibitors, and the incidence of intraventricular haemorrhage (IVH) in premature neonates." (PMID 41898459, 2026).
Kawasaki disease (1 paper, 2014). A rare inflammatory disease characterized by an acute febrile, systemic, self-limiting, medium-vessel vasculitis primarily affecting children. "Specifically, cell distribution differences of MMP-9 and the tissue inhibitor of MMP-1 in patients with Kawasaki disease." (PMID 25191698, 2014).
kidney cancer (1 paper, 2025). Primary or metastatic malignant neoplasm involving the kidney. "One study indicated an association between an MMP1 genetic variant and predisposition to kidney cancers." (PMID 40386045, 2025).
kidney damage (1 paper, 2025). "Among the different types of MMPs, MMP-1, MMP-2, and MMP-3 have been identified as particularly important in the progression of kidney damage." (PMID 40649789, 2025). "For example, in experimental studies of Adriamycin-induced nephropathy, histological cohorts were analyzed, and increased MMP-1 expression was found compared to controls, which could promote ECM accumulation and kidney damage." (PMID 40649789, 2025).
large cell carcinoma of the (1 paper, 2024). "MMP1 plays a crucial role in promoting tumor progression in large cell carcinoma of the lung by inducing fibroblast senescence." (PMID 38612764, 2024).
latent infection (1 paper, 2022). "Therefore, MMP1 may have a role in the maintenance of EBV latent infection and in development of associated cancers." (PMID 36272970, 2022).
leiomyoma (1 paper, 2013). A well-circumscribed benign smooth muscle neoplasm characterized by the presence of spindle cells with cigar-shaped nuclei, interlacing fascicles, and a whorled pattern. "An accelerated leiomyoma growth correlated with higher frequency of the MMP-1 2G allele." (PMID 24163697, 2013). "Alternatively, another work found MMP-1, MMP-2, MMP-3, and MMP-9 with higher activity of MMP-2 in leiomyoma compared to myometrium." (PMID 24163697, 2013).
leishmaniasis (1 paper, 2019). Infectious disease that is transmitted through the bite of hematophagous female phlebotomine sand flies. "An inverse correlation between FLI1 gene expression and MMP1 in cutaneous lesions has also been observed, suggesting MMP1 as a potential therapeutic target in severe forms of leishmaniasis." (PMID 30967861, 2019).
lipodystrophy (1 paper, 2022). A congenital or acquired disorder characterized by abnormal loss or redistribution of the adipose tissue in the body. "Besides, the GG genotype and the G allele of matrix metalloproteinase-1 (MMP1) were correlated with lipodystrophy in HIV patients receiving HAART." (PMID 35628408, 2022).
lymphangioleiomyomatosis (1 paper, 2023). A multifocal neoplasm with perivascular epithelioid cell differentiation affecting almost exclusively females of child-bearing age. "Similar to cells within the cysts in lymphangioleiomyomatosis (LAM), the cAS tumor cells produce matrix metalloproteinase 1 (MMP‐1; collagenase 1)." (PMID 35543776, 2023).
malocclusion (1 paper, 2025). "Candidate genes such as COL1A2, matrix metalloproteinases (MMP-1, MMP-9), and muscle-related genes (ACTN2, ACTN3) have been implicated in craniofacial morphology and malocclusion risk." (PMID 41153339, 2025).
mast cell tumors (1 paper, 2025). "In low-grade cutaneous canine mast cell tumors, the authors also observed a correlation between high CB2R immunoreactivity, the absence or light expression of the p21 protein, and strong immunoreactivity of matrix metalloproteinase-1 (MMP-1)." (PMID 40804975, 2025).
melasma (1 paper, 2022). "There was an increase in MMP1 gene expression and a decrease in collagen IV, VII (COL4A1, COL7A1), and TIMP4 expression in fibroblasts isolated from melasma skin." (PMID 35840442, 2022). "TheWNT3A, EDN3, ESR2, PTG2, MMP1, and SOD2 genes were up-regulated, whereas the COL4A1, CSF2, DKK3, COL7A1, TIMP4, CCL2, and CDH11 genes were down-regulated in melasma skin fibroblasts when compared to the ones from adjacent healthy skin." (PMID 35840442, 2022).
meningioma (1 paper, 2024). A generally slow growing tumor attached to the dura mater. "In meningiomas, the protein levels of MMP1, MMP2, and MMP3 were similar to controls, but a slight decrease in MMP8 protein levels was identified." (PMID 38474106, 2024). "We observed an increase in MMP2 mRNA levels in meningiomas compared to healthy samples, where MMP1 and MMP13 expression was not amplified in the control group." (PMID 38474106, 2024).
migraine (1 paper, 2022). "The other identified pleiotropic effects that link MMPs to migraine risk are pleiotropy at the gene level for MMP1, MMP7 and MMP12, and at the SNPs level for MMP1." (PMID 35546551, 2022).
Mitral stenosis (1 paper, 2014). An abnormal narrowing of the orifice of the mitral valve. "However the sensitivity of MMP-1 was found to be 90% in MR (AUC = 0.97) while it was about 77% in Mitral Stenosis (AUC = 0.85)." (PMID 24603967, 2014).
mucinous adenocarcinoma (1 paper, 2018). An invasive adenocarcinoma composed of malignant glandular cells which contain intracytoplasmic mucin. "A significant positive association was detected between MMP-1 immunoreactivity and smoking status (p = 0.016), Brinkmann index (p = 0.038), pathological T factor (pT) (p = 0.029), tumor size (p = 0.007), and subtype of invasive mucinous adenocarcinoma (p < 0.001)." (PMID 29463039, 2018).
mucositis (1 paper, 2022). Mucositis is inflammation and damage of the mucous membranes lining the mouth and other parts of the gastrointestinal (GI) tract. "MMP-1, MMP-2, MMP-8, and TIMP-1 activities in serum, stomach, small intestine, and large intestine were significantly higher in the Mucositis group in comparison to the Control and ALA groups (p < 0.05–0.0001)." (PMID 36290656, 2022). "In comparison to the Control and ALA groups, 5-FU treatment enhanced MMP-1, MMP-2, MMP-8, and TIMP-1 activation in sera and tissues in the Mucositis + ALA group." (PMID 36290656, 2022). "The results revealed mucositis-elevated TNF-, IL-1, MDA, MMP-1, -2, -8, and TIMP-1 levels in both tissues and sera, and these values dropped dramatically following ALA treatment." (PMID 36290656, 2022).
myoclonic epilepsy (1 paper, 2024). A group of epilepsy syndromes in which myoclonic seizures are a prominent feature. "These outcomes are supported by a study on mitochondrial disease, myoclonic epilepsy, and ragged red fiber syndrome that occur due to genetic mutations in mtDNA which impair mitochondrial respiration, induce oxidative stress, and, in skin fibroblasts, increase MMP1 expression." (PMID 39199263, 2024).
Nephrogenic systemic fibrosis (1 paper, 2021). "Nephrogenic systemic fibrosis skin biopsies display increased expression of TIMP-1, but little to no MMP-1." (PMID 35008794, 2021).
neurofibroma (1 paper, 2021). An intraneural or extraneural neoplasm arising from nerve tissues and neural sheaths. "Similar to neurofibromas in vivo, MMP1 levels were significantly reduced in NFFs compared with those in HEFs in vitro." (PMID 34011935, 2021). "The proportions of MMP1-positive stromal cells were 6.2 ± 1.4% (mean ± standard error), 3.4 ± 1.3%, and 0.3 ± 0.1% in normal control skin, perilesional area of neurofibromas, and lesional area of neurofibromas, respectively." (PMID 34011935, 2021). "To evaluate MMP1 expression in neurofibromas, we first conducted immunohistochemical analysis in neurofibromas of five neurofibromatosis 1 patients." (PMID 34011935, 2021). "We then counted the stromal MMP1-positive cells in the neurofibromas (lesional and perilesional areas) and five samples of normal healthy skin." (PMID 34011935, 2021). "An excess of MMP1 protein is released even in neurofibromatosis 1 cells, and may restore the collagen-degrading capacity and be useful for the treatment of neurofibromas." (PMID 34011935, 2021). "As we show here, CQ and HCQ can be promising drugs for neurofibroma to decrease the collagen component, which is overexpressed in cutaneous and non-cutaneous lesions, through an increase in MMP1." (PMID 34011935, 2021). "The majority of stromal cells in the neurofibroma lesions were virtually negative for MMP1 staining." (PMID 34011935, 2021). "Even in the early-stage lesions of neurofibroma, the stromal cells were MMP1-negative." (PMID 34011935, 2021).
neurofibromatosis 1 (1 paper, 2021). "We analyzed the collagen and matrix metalloproteinase 1 (MMP1) expression in Neurofibromatosis 1 cutaneous neurofibroma and found excessive expression of collagen and reduced expression of MMP1." (PMID 34011935, 2021). "In this study, we investigated the mRNA and protein expression of COL1A1 and MMP1 in dermal cell lines derived from neurofibromatosis 1 and healthy volunteers." (PMID 34011935, 2021). "In conclusion, the mRNA and protein expression of MMP1 is markedly reduced in stromal cells in neurofibromatosis." (PMID 34011935, 2021). "Agents with the potential to restore MMP1 downregulation may have therapeutic value in neurofibromatosis." (PMID 34011935, 2021). "The antimalarial drugs HCQ, CQ are feasible options to restore the MMP1 production and release in stromal cells in neurofibromatosis 1 by dual mechanisms, one by activating the AHR-ERK-MMP1 pathway and the other by inhibiting the lysosomal degradation of MMP1 proteins." (PMID 34011935, 2021).
neuroma (1 paper, 2021). A tumor that grows from a nerve or is composed of nerve cells and nerve fibers. "Notably, the number of MMP1 + stromal cells was significantly reduced in the lesional area of cutaneous neurofibromas compared with that in the perilesional area of neuromas or in normal control skin." (PMID 34011935, 2021).
neuropathy (1 paper, 2023). A disorder affecting the nervous system that manifests with pain, tingling, numbness, and/or muscle weakness. "Notably, HDL2 isolated from type 2 diabetes patients with neuropathy was more potent compared to HDL2 from patients without neuropathy in upregulating MMP-1, downregulating TIMP-1, and stimulating collagenase activity in Schwann cells." (PMID 37762318, 2023).
nodular melanoma (1 paper, 2021). "Immunohistochemistry with the use of a tissue microarray revealed that MMP1 is overexpressed in primary nodular melanoma." (PMID 34445346, 2021).
ocular hypertension (1 paper, 2025). Abnormally high intraocular pressure. "Similarly, a single intracameral injection of a glucocorticoid-inducible adenovirus vector carrying a human MMP-1 gene (AdhGRE.MMP1) lowered IOP by 70% in a steroid-induced ocular hypertension model in sheep." (PMID 39516652, 2025).
oncocytoma (1 paper, 2014). "Intriguing gene expression patterns present in the benign oncocytoma-like regions were the underexpression of metalloproteinases matrix metallopeptidase 1 and matrix metallopeptidase 7 diminishing invasiveness." (PMID 25275525, 2014).
oral candidiasis (1 paper, 2022). Infection of the mucosal lining of the mouth with the fungus Candida albicans. "Also, the expression of MMP1, MMP10, COL5A2, SERPINB4, and CRABP2 was increased under both conditions, confirming that oral candidiasis may drive OSCC progression events in vivo." (PMID 35089096, 2022).
oral cavity tumors (1 paper, 2024). "We integrated the single cell RNA-seq data analysis from 18 patients with oral cavity tumors from Gene Expression Omnibus GSE103322, and found MMP1 highly expressed in both fibroblasts and tumor cells compare to other cell types." (PMID 38320998, 2024).
oral diseases (1 paper, 2024). "As DDR1 has been verified to be significant in the development of dental and periodontal tissues and the process of oral diseases, in the present study, we focused on the mechanisms controlling DDR1-mediated MMP-1, MMP-2, and MMP-13 expression in hPDLCs to demonstrate the role of DDR1 in ERR." (PMID 39596178, 2024).
oral epithelial dysplasia (1 paper, 2007). "It has also been documented that cases of oral epithelial dysplasia showing high expression level of MMP-1 developed into OSCC at higher frequency than cases with low expression of MMP-1." (PMID 17919326, 2007). "An in situ hybridization study revealed that MMP-1 expression in normal oral mucosa is controlled at a low level, whereas a remarkably elevated expression level is observed in cases of oral epithelial dysplasia, which becomes even higher in cases of OSCC." (PMID 17919326, 2007).
oro-pharyngeal cancers (1 paper, 2017). "We have previously reported elevated levels of MMP1 and MMP14 in tissue sections from oro-pharyngeal cancer patients and also identified MMP14 as a direct p63 regulated gene in normal HFK." (PMID 26001294, 2017). "The microarray analysis of oro-pharyngeal cancers indicated increased levels of MMP1, but not MMP2, 9 and 14 in these tumours compared to normal tissue suggesting a potentially important role of MMPs in invasion." (PMID 26001294, 2017).